TNF (tumor necrosis factor)
Diseases named in the same sentence as TNF in open-access papers (continued):
Sharing a sentence is not in itself a finding about the gene and the disease.
tumor (continued). "TNF-α was found not only involved in cell transformation and proliferation, but also in tumor metastasis." (PMID 20699000, 2010). "Isothiocyanates inhibited tumor-specific angiogenesis by down-regulating nitric oxide, TNF-alpha and proinflammatory cytokine production, and by inactivation of Akt." (PMID 20534110, 2010). "Increasing tumour islet TNFα density was a favorable independent prognostic indicator (p = 0.048) while stromal TNFα density was an independent predictor of reduced survival (p = 0.007)." (PMID 20573209, 2010). "Though the exact mechanism(s) by which tumor-infiltrating macrophages enhance tumor growth is not clear, it is possible that these macrophages produce excess of PGE2, TNF-α and other pro-inflammatory molecules that aid tumor cell growth." (PMID 20932327, 2010). "Consistently, ERK activation is associated with myostatin upregulation both in the muscle of tumor-bearing animals and in TNFα-treated C2C12 myotubes, suggesting the possibility of a causal relationship between the two events." (PMID 21048967, 2010). "True to its name, high doses of regional TNF-α can lead to hemorrhagic necrosis via selective destruction of tumor blood vessels." (PMID 20699000, 2010). "Constitutive production of TNF-α from the tumour microenvironment is a characteristic of many malignant tumours and its presence is often associated with poor prognosis." (PMID 20087353, 2010). "A recent study showed that Celastrol inhibited TNF alpha-induced tumor cell invasion through inhibition of gene expression controlled by NF-κ B pathway." (PMID 20428237, 2010). "These tumour-promoting activities suggest that inhibition of TNF-α is an effective strategy for cancer therapy." (PMID 20087353, 2010). "Following activation, macrophages secrete VEGF and IL-8, but they also secrete TNF-α and IL-1, which in turn stimulate tumor cells to secrete increased levels of VEGF and IL-8." (PMID 21437225, 2010). "There was increased expression of TNFα in the tumour islets of patients with AMS compared to those with BMS (median 27.2 versus 18.8 cells/mm2 respectively, p = 0.006)." (PMID 20573209, 2010). "Previous work has shown that curcumin exerts its anti-tumor property by suppressing TNFα mediated NFκB activation." (PMID 20405005, 2010). "TNF has been suggested to play a major role in apoptosis and as an antineoplastic in the immunologic response to tumor cells." (PMID 20546618, 2010). "We showed that TNF-α greatly enhanced the migration and invasion of tumour cells by inducing the EMT programme through NF-κB-mediated Snail stabilisation." (PMID 20087353, 2010). "Strikingly, both β-catenin and Snail are highly expressed in tumour cells at the invasive front (tumour-stromal boundary) in which the level of TNF-α is elevated." (PMID 20087353, 2010). "Tumour necrosis factor-α has a particularly important role in tumour microenvironment and promotes tumour cell migration and invasion, however, the mechanism by which TNF-α facilitates these events remains elusive." (PMID 20087353, 2010). "Here, we address Smad4 dependent effects of the prominent inflammatory cytokine TNFα on tumor cells." (PMID 20307265, 2010). "Both PDTC and BAY 11-7085 produced a significant decrease in tumor cell migration (p = 0.001), and TNFα stimulation further decreased cell migration when the NF-κB pathway was inhibited (p < 0.05)." (PMID 20716363, 2010). "The synergistic effect of TNF-α combined with chemotherapy or radiotherapy is directed mainly against the tumor vasculature." (PMID 20178622, 2010). "In this work, we first showed that the CD45+ tumor fraction expressed different cytokines, among them IL-10, TNFα and TGFβ." (PMID 20525400, 2010). "Recent studies have shown that the abnormal activation of NF-κB is the main reason for TNFα tolerance in many types of tumor." (PMID 20367887, 2010). "Tumour stromal cells, including macrophages, dendritic cells and fibroblasts, generate several inflammatory cytokines such as TNF-α, IL-1 and IL-6." (PMID 20087353, 2010).
tumor (continued). "TNF-α is a potent pro-inflammatory cytokine which can be produced by tumor cells and recruited inflammatory cells at the tumor site." (PMID 20923560, 2010). "The TNF-α also induces tumour cell invasion through NF-κB- and JNK-mediated upregulation of migration-inhibitory factor (MIF) in macrophages and through enhanced MMPs production in tumour cells." (PMID 20087353, 2010). "In this study, we discuss the molecular mechanisms of TNF-α-induced tumour migration and invasion, particularly focusing on the contribution of TNF-α–NF-κB–Snail pathway." (PMID 20087353, 2010). "High doses of human recombinant TNF-α-induced haemorrhagic tumour necrosis of both syngeneic and xenografted tumours when injected locally and repeatedly." (PMID 20087353, 2010). "Other studies showed that p37 enhances tumor cell invasion in vitro, inhibits mammalian cell adhesion, and induces secretion of TNF-α from human peripheral blood mononuclear cells." (PMID 21062494, 2010). "Although TNF-α was first noted for its role in killing tumor cells, it also has pleiotropic functions including inflammatory response and host resistance to pathogens." (PMID 21108843, 2010). "At day 5, 7, 10 and 14 after operation, the expression of TNF-α in the spinal cord was higher in tumor-bearing mice compared to the sham mice." (PMID 20923560, 2010). "Surprisingly, expression of TNFα in the tumour stroma emerged as a significant independent predictor of reduced survival (hazard ratio 1.007, 95% CI 1.002 to 1.011, p = 0.007)." (PMID 20573209, 2010). "The tumour biology of TNFα however is complicated, with evidence of both pro-tumourigenic and anti-tumourigenic activity in animal models." (PMID 20573209, 2010). "Although TNF-α was named for its ability to induce hemorrhagic necrosis of tumors, there is increasing evidence that TNF-α is produced by cancer cells and acts as an endogenous tumor promoter." (PMID 22069563, 2010). "Another study linked Egr-1 to TRAIL that showed that TNF and TRAIL are released from irradiated (IR) tumour cells and induce bystander death of neighbouring/IR-unaffected cells." (PMID 20087343, 2010). "As described in more detail below, TNFα is a key tumor promotion cytokine that regulates many cellular responses including inflammation, immunity, cell proliferation, differentiation and apoptosis." (PMID 21297902, 2010). "TNF α plays also a necessary and beneficial role as mediator of host resistance to infection and tumor formation." (PMID 20640152, 2010). "Although important in the pathophysiology of RA, TNF also has many physiologic roles, including host defense and tumor surveillance." (PMID 20535785, 2010). "There is evidence that some inflammatory cytokines (such as IL-1β, IL-6, IL-23 and TNF-α promote tumor development by acting directly or indirectly on neoplastic cells." (PMID 20525350, 2010). "Our results found that kallistatin reduced the infiltrating macrophages, TNF-α production and NF-κB transcriptional activity in tumor sites." (PMID 20509975, 2010). "It was not until 1975 that an endotoxin-like substance was described in activated macrophages with tumor-regression activity and was given the name of tumor necrosis factor alpha, TNF-α." (PMID 20398373, 2010). "Mutual regulation of these cellular “safeguards” would thus certainly be beneficial for tumour cells to maintain a high level of protection against TNF-induced killing." (PMID 21307398, 2010). "The subsequent results showed the increased tumor metastasis inhibited by neutralizing TNF-α antibody." (PMID 20699000, 2010). "We here present data showing that tumor cell responses to TNFα and to the combination of TNFα and TGFβ critically depend on Smad4." (PMID 20307265, 2010). "The effector cells involved in enhancing tumor growth appear to be macrophages, which are recruited to the tumor sites and produce TNF-α to stimulate tumor growth." (PMID 20509975, 2010).
tumor (continued). "A direct relationship between tumour islet TNFα density and survival was noted (rs = 0.213, p = 0.01)." (PMID 20573209, 2010). "There is evidence that major inflammatory cytokines (such as IL-1β, IL-6, IL-23 and TNF-α promote tumor development by acting directly or indirectly on neoplastic cells." (PMID 20525350, 2010). "Tumour necrosis factor (TNF)-α is a key cytokine involved in inflammation, immunity, cellular homeostasis and tumour progression." (PMID 20087353, 2010). "We will emphasise the contribution of TNF-α and the nuclear factor-κB pathway on tumour cell invasion and metastasis." (PMID 20087353, 2010). "We have shown previously that in patients with extended survival, there is increased expression of macrophages in the tumour islets compared to patients with poor survival, and that in a separate study the majority of tumour islet macrophages expressed TNFα." (PMID 20573209, 2010). "This study used immunohistochemistry to investigate the expression of TNFα in the tumour islets and stroma with respect to survival in 133 patients with surgically resected NSCLC." (PMID 20573209, 2010). "Expression of TNFα in the tumour islets emerged as a significant independent predictor of survival (hazard ratio 0.995, 95% CI 0.989 to 1.000, p = 0.048)." (PMID 20573209, 2010). "aCD4S or the combination of 160 U/ml of IFN-γ and 11.2 ng/ml of TNF-α were used to presensitize tumor cells for 48 hrs, followed by irradiation." (PMID 20178622, 2010). "In mammalian cells, they inhibit lysine 63-type polyubiquitylation of PCNA, inhibit activation of NF-κB by TNF-α and sensitize tumor cells to chemotherapeutic agents." (PMID 20613989, 2010). "It is plausible that TNF has different roles at different concentrations during different stages of tumor genesis." (PMID 20535785, 2010). "There are two families of costimulatory molecules expressed in antigen presenting cells (APCs) and some tumor cells: B7 and TNF/TNF receptor (TNF-R)." (PMID 20140259, 2010). "Using the NF-κB inhibitor DHMEQ, Yamashita and colleagues showed decreased tumor growth, cancer cell invasion, increased apoptosis, as well as TNFα- and taxane-induced apoptosis in a single ATC cell line." (PMID 20492683, 2010). "Although drug treatment was discontinued on day 7, compared with tumor receiving vehicle group, tumor receiving thalidomide group still showed a decrease in the expression of TNF-α at day 14 after operation." (PMID 20923560, 2010). "The proinammatory cytokines interferon-γ and TNF-α can induce UBD expression in conjunction with an immune response within the tumour microenvironment." (PMID 20808312, 2010). "The same authors also showed co-expression of HERG and TNFα on cell membrane of tumour cells, leading to increased activity of the transcription factor nuclear factor kappa B facilitating tumour cell proliferation." (PMID 21190577, 2010). "TNFα is produced by tumor cells and can induce autocrine proliferation and disease progression in ovarian cancer." (PMID 21318181, 2010). "When divided into tertiles, there was significantly improved survival in the top tertile of TNFα expression in the tumour islets compared to the middle and lower tertiles." (PMID 20573209, 2010). "Antigen-presenting cells migrate into and out of tumour tissue to present tumour antigen to T-helper cells, as well as to produce cytokines, such as interleukin-1 beta and TNF-alpha that stimulate T-helper cells." (PMID 21461373, 2010). "Further support for the biological relevance of the observed trafficking of RGD-A-TNF along with targeted expression of human TNFα, was provided by the objective anti-tumor activity observed in dogs receiving multiple weekly treatments." (PMID 19330034, 2009). "Compared with the 4T1 tumor-bearing Balb/c mice, significant increase in the levels of M-CSF (1.5 fold), IL-17 (1.5 fold), TNF-α, VegF, and IL-6 (1.2 fold) was observed in the 4T1 tumor-bearing arthritic mice." (PMID 19643025, 2009).
tumor (continued). "In this report, we describe a targeted delivery of TNFα with an AAVP gene delivery system to tumor blood vessels of pet dogs with spontaneous cancer." (PMID 19330034, 2009). "Our data further suggest that TNF-α in concert with other pro-inflammatory cytokines plays an important role in efficient bacterial tumor colonization." (PMID 19693266, 2009). "Taken together our results show that TNF-α among other pro-inflammatory cytokines plays an important role in the early phase of bacterial tumor-colonization." (PMID 19693266, 2009). "Through a step-wise trial design we demonstrated the safety, tumor-selective trafficking, and anti-tumor activity of RGD-A-TNF to tumor blood vessels and targeted expression of TNFα in a relevant clinical setting." (PMID 19330034, 2009). "With the tumor progressed, this picture changed: IL-10 production increased and TNF-α and IFN-γ production decreased, and the animals showed extensive fungal dissemination." (PMID 19534779, 2009). "In previously published work in mouse xenograft models, we described targeted systemic delivery of RGD-AVVP vectors expressing either HSVtk or TNF-α, to tumor vasculature." (PMID 19330034, 2009). "Determination of hemoglobin content in CT26 tumors after i.v. injection of 200 μg TNF-α into tumor bearing mice confirmed these results." (PMID 19693266, 2009). "Our results demonstrated that the mice produced more IFN-γ and TNF-α and less IL-10, and also exhibited fungal clearance, at the beginning of tumor evolution." (PMID 19534779, 2009). "TNF-α is rarely cytotoxic to tumor cells and promotes cancer growth, invasion and metastasis, and controls the infiltration of antitumor lymphocytes." (PMID 19698142, 2009). "Mouse body weight, which is used as a major indicator of TNF toxicity, and tumor mass volumes were assessed over time." (PMID 19740430, 2009). "A number of factors secreted from tumor cells, such as IL-1, tumor necrosis factor-α and VEGF, induce the expression of Del1 in vascular endothelial cells." (PMID 19292890, 2009). "It has been reported that in the early cancer stage, TNF plays the role as tumour repressor, but in the late cancer stage, it promotes cell proliferation." (PMID 19640296, 2009). "While Salmonellae quickly accumulated and grew in CT26 tumors, tumor colonization after treatment with anti-TNF-α was slightly delayed." (PMID 19693266, 2009). "Our study has extended these observations by demonstrating that a tumoricidal function of TAMs, namely secretion of TNF-α, is lost at a relatively late point in tumor growth." (PMID 19226468, 2009). "Further activation of IFNγ-primed macrophages with antibody-coated tumor cells (indicated as RR in the figure) resulted in significantly higher levels of TNFα in presence of DMSO." (PMID 19148288, 2009). "We pre-treated γδ T-cells with chemical inhibitors that specifically block those pathways and then analyzed the effects on cell activation, proliferation, TNFα secretion and tumor cell killing." (PMID 19479075, 2009). "Gene therapy using expression of the tumor necrosis factor regulated by the Egr-1 promoter has already been used in humans for tumor therapy." (PMID 19765320, 2009). "Tumor-induced platelet aggregation is believed to protect tumor cells from immunological assault in circulation; platelets protect tumors from TNF-α-mediated cytotoxicity." (PMID 19570195, 2009). "Increase in soluble TNF receptors can inhibit TNF signaling and has been shown to prevent TNF-mediated tumour lysis." (PMID 19690616, 2009). "TNF-α can be secreted by immune-related cells and tumour cells, and it has been suggested to act in an autocrine/paracrine way to promote cancer development." (PMID 19904265, 2009). "RFA has a strong catabolic effect on tumor cells that are producing nerve-stimulating cytokines such as tumor necrosis factor-alpha (TNF-α), interleukins (IL-1 and IL-6), resulting in inhibition of osteoclast activity." (PMID 19917114, 2009).
tumor (continued). "Tumour-associated macrophages are known to contain many proangiogenic factors, such as VEGF, TNF-α, CXCL-8, bFGF and proteases such as MMP-2 and MMP-9." (PMID 19352388, 2009). "Our observations indicate that tumor-colonizing Salmonellae provoke effects in tumor blood vessels that resemble vascular disrupting agents (VDAs) or TNF-α." (PMID 19693266, 2009). "In other studies, TNF-α level was lower in HCC tumor tissue versus the tissue surrounding the tumor and in HCC patients versus healthy individuals." (PMID 27942274, 2009). "NDGA has been shown to exert anti-tumor effects and to block apoptosis induced either by tumor necrosis factor-α (TNF) or CD95 ligand." (PMID 19133137, 2009). "Here we analyzed changes in the content of VCAM-1 in endothelial cells under experimental treatments with TNF or TFS's that led to an increase in tumor cell adhesion." (PMID 19930605, 2009). "Instead, TNF-α was detectable between 30 min to 2 h p.i. at high concentrations in blood of infected tumor-bearing mice." (PMID 19693266, 2009). "The priming of macrophages with IFNγ leads to the up-regulation of Fcγ receptors, TNFα, and inducible nitric oxide synthase (iNOS); all of which can enhance the killing of tumor cells." (PMID 19148288, 2009). "Activated Vγ9Vδ2 T-cells are known to secrete large amounts of IFNγ and TNFα, very potent anti-tumor mediators in vivo." (PMID 19479075, 2009). "Inflammatory cells in the tumor microenvironment secrete TNF-α and other cytokines that positively contribute to tumor progression." (PMID 19534786, 2009). "Tumor cells can manipulate the immune microenvironment to their advantage, for example, by promoting TNF-α secretion." (PMID 19698142, 2009). "At the final time points examined (tumor morbidity or 40 dpi), there was an increase in the frequency of TAMs with decreased capacity to secrete TNF-α." (PMID 19226468, 2009). "Through this established infrastructure, the first trial of the COTC (COTC001) evaluated a targeted AAV-phage vector delivering tumor necrosis factor (RGD-A-TNF) to αV integrins on tumor endothelium." (PMID 19330034, 2009). "Only one patient who was treated with ILP with TNF-alpha and melphalan responded to that treatment, with a necrosis of 70% of the tumor." (PMID 18593459, 2008). "Tumor cells can show elevated NF-κB-regulated transcription, which can inhibit TNF-α-induced apoptosis through the up-regulation of the anti-apoptotic proteins of the Bcl-2 family." (PMID 18336718, 2008). "Studies from our laboratory showed that curcumin neutralized tumor-induced oxidative stress, restored NF-kB activity, and inhibited TNF-α production, thereby minimizing tumor-induced T-cell apoptosis." (PMID 18834508, 2008). "Significant surface expression of CD86 and CD80 and MHC-II molecules was noted in DCs 48 hours post-electroporation with tumor cell RNA in the presence of TNF-α and LPS." (PMID 18445282, 2008). "The expression of numerous cytokines, that are growth factors for tumor cells (IL-1β, TNF, IL-6, EGF) are also regulated by NF-kB." (PMID 18336718, 2008). "Strikingly, VA Qu Spez-treated DCs activated tumor antigen specific CTL clone as analyzed by the secretion of cytokines TNF-α and IFNγ." (PMID 18533025, 2008). "Inflammatory cytokines such as TNF-α, IL-1 and IL-6 are involved in angiogenesis, which is fundamental step in tumour development." (PMID 18201386, 2008). "Such macrophages are thought to express higher levels of inflammatory cytokines (for example, TNF, epidermal growth factor and vascular endothelial growth factor), promoting angiogenesis, tumour growth and invasion." (PMID 19014637, 2008). "Production and activation of MMPs is dependent on various cytokines, including TNFα and IL-1 secreted by tumour cells, fibroblasts and macrophages." (PMID 19014637, 2008).